TNF (tumor necrosis factor)
Diseases named in the same sentence as TNF in open-access papers (continued):
Sharing a sentence is not in itself a finding about the gene and the disease.
depression (continued). "For a long time, TNF-α has been one of the molecules at the core of the study of the cytokine hypothesis of depression, and it has been consistently reported to be associated with the pathogenesis of depression." (PMID 39928658, 2025). "Similarly, anti-inflammatory drugs targeting cytokine pathways, such as IL-6 or TNF-α inhibitors, are being explored as adjunctive treatments for depressive disorders associated with chronic inflammation." (PMID 40002916, 2025). "Indeed, higher IL-13 levels are associated with more severe depression and a higher number of suicide attempts, and elevated levels of IL-2, TNF-a, and IL-8 are associated with depressive symptoms in clinical studies." (PMID 39297528, 2024). "However, due to the close association of TNFα and IL-1β with the pathophysiological processes of anxiety and depression, these two markers were explicitly investigated." (PMID 38731995, 2024). "Furthermore, increased C reactive protein, TNF-α, and pro-inflammatory cytokines are associated with depression and T2DM." (PMID 39036053, 2024). "Furthermore, acupuncture reduces inflammatory markers like LPS, TNF-α, and IL-1β in serum and brain, which are linked to anxiety and depression, suggesting dual benefits for gut and mental health." (PMID 38452033, 2024). "As a pro-inflammatory factor, TNF-α has been implicated in the pathogenesis of depression." (PMID 38377025, 2024). "In this study, we investigated the relationship between plasma cytokine levels and suicide risk stratification in adolescents with depression, and found high levels of IL-6, TNFα, IFN-γ, and IL-10 in the high-suicide-risk group, which is consistent with the results of previous studies." (PMID 39882160, 2024). "TNF-α inhibitors have been linked to paradoxical reactions, lupus, severe infections (with a slightly elevated risk), tuberculosis, and psychiatric conditions such as anxiety and depression." (PMID 38571822, 2024). "Anxiety and depression are also associated with inflammation metabolism that can be modulated by the gut through release of cytokines (interleukin (IL)-10, IL-6, tumor necrosis factor (TNF)-alpha, etc.)and inflammasome activation." (PMID 39161523, 2024). "Increased levels of TNF-α accelerate the breakdown of neurotransmitters, such as serotonin, which are deficient in depression; this may potentially contribute to the association with suicidality in patients with AD." (PMID 38541828, 2024). "Finally, a negative association between interleukin-6 (IL-6) and Rosenberg Self-Esteem Scale (Beta=-0.019, p=0.019) and a positive association between TNF-α and the Center for Epidemiologic Studies Depression Scale Revised (Beta=0.003, p=0.015) were found." (PMID 37529617, 2023). "Given the epidemiological associations identified between IL-6, tumor necrosis factor (TNF)-α, and subsequent depression, the levels of these pro-inflammatory cytokines have also been studied as potential moderators of the depressed mood response to endotoxins." (PMID 37509542, 2023). "A dysregulated HPA axis activity is proposed to be accompanied by the overproduction of pro-inflammatory cytokines such as tumor necrosis factor alpha (TNF-α), interleukin (IL)-6, or IL-1β, which leads to the loss of hippocampal neurogenesis and promotion of depression-like behaviors." (PMID 37238920, 2023). "Moreover, decreased IL-6 and TNF-α levels are associated with hippocampal size and antidepressant efficacy, highlighting the role of neuro-inflammation in depression and psychiatric disease." (PMID 37699900, 2023). "The levels of tumor necrosis factor-alpha (TNF-a) interleukin-1 beta (IL-1b), and interleukin 6 (IL-6) were found to be associated with depression severity as measured by BDI II, while levels of Interleukin-2 (IL-2) were found to be correlated with anxiety measured by STAI-state." (PMID 37250694, 2023).
depression (continued). "The increased prevalence of depression in RA patients may be partially explained by the involvement of several immunological changes linked to RA such as upregulation of IL-6 and TNF-α are in depressive illness." (PMID 38299049, 2023). "Animal experience revealed that PM might cause neurotoxicity by inducing microglia activation characterized by the release of TNFα, which damages the olfactory bulb and increases depression risk." (PMID 37280568, 2023). "In addition, soluble TNF receptor-1 (sTNFR-1) was significantly associated with depression in COPD, while depression ratings have been positively associated with plasma TNF-α levels in COPD." (PMID 37048736, 2023). "In another study, spared nerve injury (SNI)-induced depression was associated with the activation of microglia through the upregulation of Iba1 and CD11b and increased levels of pro-inflammatory mediators (IL-1β, TNF-α, and CD68) in the PFC54." (PMID 36747075, 2023). "Our results do not show a deniable association between immune system activity and MDD, thus, it is plausible that other inflammatory profiles, besides CRP, IL-6 and TNF, may be associated with different depression subtypes." (PMID 36966195, 2023). "Together, these findings suggest that increased IL-6, TNF-α and neopterin may be associated with increased depression, including in people living with HIV." (PMID 37693812, 2023). "Multiple studies have suggested that TNF-α and IL-6 levels are increased remarkably in the peripheral blood of depressed patients than in healthy controls, suggesting a strong association between inflammatory cytokines and depression." (PMID 37881439, 2023). "Furthermore, resistance exercise exerts an anti-inflammatory effect by down-regulating pro-inflammatory markers such as TNF-α and IL-1β mRNA, which have been implicated in depression." (PMID 37333923, 2023). "There are shared inflammatory mechanisms implicated in both depression and cancer such as the increasing IL‐6 and TNF‐α levels, furthermore, treatments for cancer can promote cancer‐related pain and further inflammation by enhancing cytokine production by noncancerous cells." (PMID 37991167, 2023). "IL-6, TNF-α and IL-1, and their association to depression could be linked to their ability to trigger the activation of HPA axis." (PMID 36911685, 2023). "The CDAI was developed based on its combined effect on anti-inflammatory effects based on the pro-inflammatory markers Tumor Necrosis Factor-α (TNF-α) and Interleukin-1β (IL-1β), which are associated with many health outcomes, including depression, all-cause mortality, colorectal cancer, etc.." (PMID 37063339, 2023). "Elevated levels of TNF-α and IL-6 in the cerebrospinal fluid and brain parenchyma of patients with depression may be associated with enhanced microglial activity and decreased levels of astrocyte and oligodendrocyte markers." (PMID 37840923, 2023). "TNF-α and IL-8 levels that are abnormal are linked to depression." (PMID 38299049, 2023). "In conclusion, our study had shed light on that gene polymorphisms as suggestive risk predictors and expression levels of IDO1 were involved in depression occurring during the acute stage of stroke and the TNF-α rs361525 polymorphism was associated with serum IDO1 levels." (PMID 36911716, 2023). "Likewise, the correlation showed impairment of habituation memory and depression behavior associated with brain cyst load and elevated systemic levels of IFNγ and TNF." (PMID 35572567, 2022). "Indeed, in a cumulative meta-analysis in adult patients with clinical depression, conducted on 58 observational studies, it was concluded that IL-6, CRP, and TNF-α were more strongly associated with severe depression than with moderate depression." (PMID 35360574, 2022). "Thus, pro-inflammatory mediators, such as interleukin (IL)-6, IL-17, and tumor necrosis factor (TNF)-α, have been associated with depression in SpA." (PMID 36294416, 2022).
depression (continued). "Similarly, our previous review has demonstrated that depression and anxiety are associated with elevated TNF-α, IL-6, IFN-α, and C-Reactive Protein (CRP) levels." (PMID 35053845, 2022). "We analyzed plasma IL-1β, IL-2, -6, -8, -10, TNF, kynurenine, tryptophan, serotonin, kynurenic- quinolinic- and picolinic acids and used mixed-effects models to assess the association between biomarkers and depression severity." (PMID 35078975, 2022). "This herbal product was proven to prevent drug-induced pulmonary fibrosis in a mice model by decreasing the plasma levels of inflammatory cytokines, like TNF-α, interleukin citation(IL)-1, and IL-6; these mediators have been implicated in the development of depression." (PMID 36059752, 2022). "Also, TNF and rQK in the 2nd trimester, were strongly associated with depression severity in the 3rd trimester (EPDS)." (PMID 35078975, 2022). "However, individuals having a homozygous rare allele for the rs1799964 SNP of TNF-α would have decreased depression severity, as evidenced by the lower odds of these individuals being in the subsyndromal class of depression." (PMID 35528795, 2022). "The Traditional Chinese Medicine Systems Pharmacology Database (TCMSP), the Analysis Platform, DrugBank, and other databases were analyzed using data mining, and the results show that the active components of HP and depression are linked to targets such as TNF-, IL-2, TLR4, and so on." (PMID 36556951, 2022). "Besides, depression relates to the disorder of immune system, and the expression of inflammation markers (IL-6, C-reactive protein, TNF-α) increases the risk of DN." (PMID 36538528, 2022). "In this context, the use of cocaine and crack has been shown to trigger immunomodulatory effects; the TNF alpha cytokine has been associated with the activation of the serotonergic system in patients with depression, suggesting a close relationship between cytokines and serotonergic systems." (PMID 37274848, 2022). "• Depression is associated with higher concentrations of IL-6, IL-10, TNF-α, and VEGF." (PMID 35836664, 2022). "However, increased peripheral TNF-α levels led to weight loss in a mouse model of sickness and depression- and anxiety disorder-relevant behavior via different pathways." (PMID 34440067, 2021). "Proinflammatory cytokines TNFα and IL-1β could alter the neural activity of the amygdala, which is implicated in the pathophysiology of pain, depression, and anxiety." (PMID 34025342, 2021). "•The association of BDNF-levels and depression severity depends on the level of TNF-α." (PMID 34841285, 2021). "However, a significant interaction between TNF-α and BDNF was demonstrated: the association of BDNF-level and depression severity depends on the TNF-α level." (PMID 34841285, 2021). "Furthermore, previous studies have revealed that functional allelic variants of the IL-1β and TNF-α genes increase the risk of depression and are associated with decreased responsiveness to antidepressant therapy." (PMID 34490521, 2021). "Furthermore, 28% of rats with T12 contusion SCI suffered from depression which was associated with increased serum levels of interleukin (IL)-6 and IL-1α before and IL-6 and tumor necrosis factor (TNF)-α after injury." (PMID 34220440, 2021). "In rodents, depression-like behavior induced by the use of chronic social defeat stress, male sterility, and luteinizing hormone has been associated with higher levels of pro-inflammatory IL-1β, IL-6, and TNF-α." (PMID 34531719, 2021). "Indeed, some genetic epidemiological studies have shown significant associations between the severity of depression and polymorphisms in inflammatory cytokine genes encoding IL-1β, IL-6, TNF and CRP." (PMID 34351967, 2021). "•The TNF-α/BDNF ratio is positively associated with depression severity." (PMID 34841285, 2021).
depression (continued). "Although TNF-α plays an important role in the host defense against pathogen invasion, dysregulation of TNF-α production has been implicated in a variety of human diseases including Alzheimer’s disease, cancer, major depression and inflammatory bowel disease (IBD)." (PMID 34072918, 2021). "However, none of the previously conducted meta-analysis studies reported any association of depression or its severity with IL-6, IL-1β, and TNF-α." (PMID 34975391, 2021). "In addition, depression has been associated with inflammatory factors, for instance, increased levels of pro-inflammatory cytokines including interleukin (IL)-6, tumor necrosis factor (TNF) α, and IL-1β." (PMID 33352710, 2020). "Specifically, MDD is accompanied by immune dysregulation, resulting in increased production of proinflammatory cytokines (e.g., interleukin (IL)-6 and tumor necrosis factor (TNF)-α), which could lead to depression-linked abnormalities in brain function." (PMID 32230840, 2020). "Patients treated with anti-TNF drugs have a slightly increased risk for psychiatric side effects such as depression, anxiety and insomnia that may increase the rate of psychotropic drug use." (PMID 32072134, 2020). "We speculate that cytokines manufactured in macrophages following the miR-146a-5p treatment are likely the cause of CM depression as cytokines such as both IL-6 and TNF-α are known cardiac depressants." (PMID 32958516, 2020). "In these studies, depression is associated at it's peak with high levels of general inflammation markers such as C-reactive protein (CRP) as well as high levels of pro-inflammatory cytokines such as tumor necrosis factor alpha (TNFα) and interleukin 6 (IL6)." (PMID 33240126, 2020). "Since our previous study has demonstrated that TNF‐α is a common risk factor in depressive disorders induced by both stress and inflammation, we further investigated whether antidepressant effect of TLR4 is via inhibition of TNF‐α production." (PMID 31945269, 2020). "Thus, 5-HT modulation can alleviate various TNFα-mediated inflammatory diseases, depressive disorders linked to systemic inflammation and GI disorders." (PMID 32973771, 2020). "The present study had established a direct causal association between proinflammatory cytokines and withdrawn/depression, preclinical and clinical evidence show that the peripheral administration of pro-inflammatory cytokines, such as TNF-α, can prompt depression-like behavior." (PMID 31333511, 2019). "Furthermore, inflammatory markers such as CRP, IL-6, and TNF-α have been associated with development or severity of psychiatric disorders such as depression, psychosis, and bipolar disorder." (PMID 31170007, 2019). "Major depressive disorder is also associated with increased plasma levels of proinflammatory cytokines, such as interleukin (IL)-6 and tumor necrosis factor (TNF)-α, that may play a role in the disease’s pathogenesis." (PMID 31847190, 2019). "We elaborated on these findings by investigating whether pharmacologically inhibiting TNFα signaling could ameliorate the anxiety- and depression-like behavior caused by S1PR3 knock-down." (PMID 31316053, 2019). "Furthermore, elevation of TNF-α and IL-6 levels was associated with a lower VT score, as well as a lower score for MH (which is used for detection of depression) in subjects with pulmonary hypertension." (PMID 31394768, 2019). "Nevertheless, during later stages of infection chronic exposure to low concentrations of TNF (Wajant, Pfizenmaier, & Scheurich, 2003) may contribute to the wasting syndrome, depression, and cachexia associated with CWD." (PMID 31788200, 2019). "Secondly, depression is associated with the hyperactivity of immune inflammatory responses as manifested by elevated expression of proinflammatory molecules, such as IL-6 and TNF-α." (PMID 29861834, 2018).
depression (continued). "During neuroinflammation in depression-associated behavior, inflammatory mediators such as TNF produced by activated microglia and brain-infiltrating immune cells trigger intracellular signaling cascades that can alter mitochondrial metabolism, ROS formation, and programmed cell death." (PMID 30687139, 2018). "In particular, TNFα and IL-6 have been associated with antidepressant-resistant depression." (PMID 30423923, 2018). "In addition, higher IL-1β and TNF-α levels were associated with higher Hamilton Depression Rating Scale (HAMD) scores, while higher IL-8 levels were associated with lower HAMD and Hamilton Anxiety Rating Scale scores." (PMID 29856741, 2018). "Diets with higher n-6: n-3 PUFA ratios, for example, may enhance risk of both depression and inflammatory diseases, characterized by higher levels of IL-6 and TNF-α." (PMID 30445703, 2018). "Dysregulation of the production of cytokine tumor necrosis factor α (TNFα) in the cell is known to be associated with the development of various human diseases including Alzheimer’s disease, major depression, inflammatory bowel disease, disorders of glucose and lipid metabolism, and cancer." (PMID 30586922, 2018). "In the presence of post-stroke depression, serum TNF-α concentration is higher in T-carriers (high-risk genotype) than in non-T carriers (low-risk genotype), indicating that 805 C/T genotype moderates serum TNF-a levels especially in the presence of depression." (PMID 30310056, 2018). "Thus, the number of episodes was significantly associated with increasing levels of TNFα and IL-1, while greater increases in serum sIL-1RA and IL-6 were established in puerperal women who had suffered from a lifetime depression." (PMID 29103192, 2018). "Age-related chronic low-grade inflammation is associated with elevations in circulating interleukin-6 and tumor necrosis factor-α, and they have been reported as a common factor for the occurrence of sarcopenia as well as and the development of cognitive impairment and depression." (PMID 29845019, 2018). "These associations included: higher IL-6 and IL-8 were associated with a higher incidence of depression at 6 months, TNF-a levels with depression at 12 months, IL-5/IL-8/IL-12/TBF with apathy at 12 months, TNF-a with disinhibition at 12 months, and sVCAM/sICAM/sFAS with depression at 6 months." (PMID 28740480, 2017). "Sickness behavior is not routinely measured in humans but it is of interest that elevated systemic TNF-α was associated with a 2-fold increase in neuropsychiatric features in AD patients, including apathy, anxiety, depression and agitation, which are also characteristic of sickness behavior." (PMID 27633985, 2017). "In the experiment to figure out the mechanism, there is still uncertainty about whether TNF-α inhibitors have any direct effect on depression or whether they are indirectly improving depression by recovering the underlying physical condition." (PMID 27187381, 2016). "TNF-α may underlie the mechanism of depression by an activation of the hypothalamo-pituitary-adrenocortical (HPA) axis, an activation of neuronal serotonin transporters and the stimulation of the indoleamine 2,3-dioxygenase which leads to tryptophan depletion." (PMID 26732584, 2016). "In this paper, we begin review by providing a brief overview of TNF-α and the central nervous system (CNS), and then summarize evidence from clinical and animal studies, which suggest that TNF-α may be capable of causing mood swings and depression." (PMID 27187381, 2016). "In SLE, sera TNF-α levels were independently associated with depression and with disease activity." (PMID 26732584, 2016). "Thus, the balance between TNF-α and IL-10 in maternal prenatal serum was associated with depression in a sex-dependent manner." (PMID 27244231, 2016).